GDF1 (growth differentiation factor 1)
Description:
May mediate cell differentiation events during embryonic development.
Synonyms: CHTD6; DORV; DTGA3; RAI
Tractability: Antibody: UniProt places it where antibodies can reach, with medium confidence; UniProt predicts a signal peptide or a membrane-spanning region; its Gene Ontology location is reachable by antibodies, with medium confidence.
Gene: Protein-coding gene on chromosome 19 (18,868,545 to 18,896,158, reverse strand). Ensembl gene ENSG00000130283.
Subcellular location: Secreted
Pathways (Reactome):
Developmental Biology: Signaling by NODAL
Gene Ontology:
Molecular function: cytokine activity; growth factor activity
Biological process: BMP signaling pathway; regulation of transmembrane receptor protein serine/threonine kinase signaling pathway
Cellular component: extracellular region
Genetic constraint (gnomAD): Loss-of-function variants: 10 observed, 4.48 expected, observed/expected ratio (o/e) 2.23. That is too few expected variants to judge how well the gene tolerates losing a copy. Missense variants: 442 observed, 294.84 expected, observed/expected ratio (o/e) 1.5, 90% interval 1.39 to 1.62. Synonymous variants: 238 observed, 142.84 expected, observed/expected ratio (o/e) 1.67, 90% interval 1.5 to 1.85.
Homologues: Orthologues: chimpanzee GDF1 (99% identical), macaque GDF1 (94% identical), dog GDF1 (82% identical), guinea pig GDF1 (76% identical), mouse Gdf1 (68% identical). Paralogues in human: GDF3 (35% identical), BMP4 (25% identical), BMP2 (24% identical), GDF5 (24% identical), BMP8A (24% identical), BMP8B (24% identical), GDF7 (23% identical), GDF10 (22% identical), BMP7 (22% identical), GDF6 (22% identical), GDF2 (22% identical), BMP6 (21% identical), and 19 more.
Diseases named in the same sentence as GDF1 in open-access papers:
GDF1 is named in the same sentence as 18 diseases in open-access papers, as found by Europe PMC text mining. Sharing a sentence is not in itself a finding about the gene and the disease. The quoted sentences say what the papers report.
hepatocellular carcinoma (3 papers, 2021 to 2025). A malignant tumor that arises from hepatocytes. "Growth and differentiation factor 1 (GDF1) is the member of TGF‐β superfamily that shows high expression profile in weakly differentiated high‐grade hepatocellular carcinoma (HCC)." (PMID 36625080, 2023). "Ectopic expression of GDF1 can induce the dedifferentiation of hepatocellular carcinoma (HCC) cells into their ancestral lineages and reactivate a broad panel of cancer testis antigens (CTAs), which further stimulate the immunogenicity of HCC cells to immune-based therapies." (PMID 34880251, 2021).
Tetralogy of Fallot (3 papers, 2015 to 2022). A congenital cardiac malformation comprising pulmonary stenosis, overriding aorta, ventricular septum defect, and right ventricular hypertrophy. "Mutations in NKX2-5 (5q35.1), GATA4 (8q23.1), ZFPM2 (8q23.1), GATA6 (18q11.2), GDF1 (19p13.11), JAG1 (20p12.2), and TBX1 (22q11.21) have been reported in sporadic cases with tetralogy of Fallot; however, interaction of these genes and FMR1 gene has never been reported." (PMID 28751920, 2017).
congenital heart disease (2 papers, 2023 to 2025). A heart disease that is present at birth. "At birth, individual WES was performed and a heterozygous variant was identified, probably pathogenic in the GDF1 gene (c.885C>A; p.Tyr295*), associated with multiple types of congenital heart disease (MIM#613854)." (PMID 40918675, 2025).
right atrial isomerism (2 papers, 2015 to 2024). "Both Alagille Syndrome 1 ALGS1 (MIM:118450) and Right Atrial Isomerism RAI (MIM:208530) not only share phenotypic similarities with TOF such as pulmonary stenosis (ALGS1) and complete atrioventricular septal defects (RAI), but also have disease genes in common with TOF, namely JAG1 and GDF1." (PMID 38200084, 2024).
gastric cancer (1 paper, 2022). A primary or metastatic malignant neoplasm involving the stomach. "The abnormal expression of GDF1 is closely related to the poor prognosis of gastric cancer, liver cancer, and other tumors and GDF1 is a member of the transforming growth factor beta superfamily (TGF-β)." (PMID 36518627, 2022).
liver cancer (1 paper, 2022). An epithelial or non-epithelial malignant neoplasm that arises from the liver. "A previous study showed that the expression of GDF1 in poorly differentiated liver cancer was significantly increased and overexpression of GDF1 inhibited cell proliferation but significantly increased tumor invasion and metastasis in vivo and in vitro." (PMID 36518627, 2022).
ovarian carcinoma (1 paper, 2020). A malignant neoplasm originating from the surface ovarian epithelium. "Once the presence of EpCAM positive CTCs in the blood of patients was confirmed using two methodologies, an expression profile analysis, including a panel of genes related to cell plasticity and ovarian cancer aggressiveness (MUC1, CK19, CXCR4, TIMP1, ALDH1, CD24, CD44, GDF1), was carried out." (PMID 32423054, 2020).
salivary gland adenoid cystic carcinoma (1 paper, 2013). An adenoid cystic carcinoma arising from the salivary gland. "Gdf1 is correspondingly underexpressed in salivary gland adenoid cystic carcinoma suggesting a potential role as a tumor suppressor." (PMID 23861820, 2013).
ventricular septal defect (1 paper, 2024). The presence of a defect (opening) in the septum that separates the two ventricles of the heart. "Congenital heart defects, Multiple Types CHTD6 (MIM: 613854) (formerly Transposition of the great arteries DTGA3) often have ventricular septal defects and associations between CHTD6 and the TOF-associated gene GDF1 have been reported in the literature." (PMID 38200084, 2024).
cancer (7 papers, 2017 to 2025). A tumor composed of atypical neoplastic, often pleomorphic cells that invade other tissues. "Although overexpression of GDF1 itself strongly induced tumour dedifferentiation and metastasis, a shift in cancer cellular lineages exposed an Achilles heel for immune surveillance, the CTAs." (PMID 34880251, 2021). "Taken together, our findings indicated that GDF1 is reactivated in high-grade HCCs and promotes the strong metastatic ability of this cancer." (PMID 34880251, 2021). "Until now, little was known about the expression and role of GDF1 in cancer cells." (PMID 40153751, 2025). "Taken together, this suggests that high expression of GDF1 could enhance cancer patients' sensitivity to immunotherapy." (PMID 36518627, 2022). "The present study focused on GDF1 because it is closely linked to poor tumor differentiation, while SLIT1 possesses significant oncogenic potential and is responsible for the development and metastasis of various types of cancers." (PMID 36364024, 2022). "Finally, within the list of upregulated genes in the UCHL1 KD we also found several cancer-associated genes such as SERPINB4, FGF21, NUPR1, SBSN, GDF1, HMOX1, or SOCS2, which suggested the activation of potential compensatory mechanisms in these KDs cells." (PMID 28472177, 2017). "Here the authors show that GDF1, a member of the TGF-β superfamily, is highly expressed in high-grade poorly differentiated HCC and is associated with tumor plasticity, and that GDF1-induced reexpression of cancer testis antigens could render tumors sensitive to immune checkpoint inhibition." (PMID 34880251, 2021). "In addition, FNDC4 was negatively correlated with AFP, a tumor marker of HCC, and other cancer-related genes such as AHSA1, GDF1, GPC3 and MDK." (PMID 38021165, 2023).
tumor (6 papers, 2013 to 2025). "We found that FNDC4 was inversely correlated with AHSA1 and GDF1, two novelly identified genes that were shown to be positively associated with tumor progression in HCC." (PMID 38021165, 2023). "In the present study, the secreted protein growth and differentiation factor 1 (GDF1) is found to be closely associated with poor tumour differentiation." (PMID 34880251, 2021). "A clinicopathological association study indicated that high expression of GDF1 was significantly associated with adjacent invasion, clinical stage, tumour relapse, and poor differentiation (two-sided χ2 test)." (PMID 34880251, 2021). "Unlike TGF-β, which is universally expressed in both normal and tumour tissues, the expression of GDF1 was restricted to high-grade HCCs and associated with the reactivation of CTAs." (PMID 34880251, 2021). "A significant progressive increase in GDF1 from low-grade tumours to high-grade tumours was found in both the HKU cohort and TCGA cohort." (PMID 34880251, 2021). "Since GDF1 was isolated from high-grade tumours, we further measured the expression of GDF1 in subgroups of patients with different tumour grades." (PMID 34880251, 2021). "IHC staining also confirmed the high expression of GDF1 in poorly differentiated tumours compared with moderate- and well-differentiated tumours." (PMID 34880251, 2021). "Here, we show that GDF1-induced tumour plasticity can sensitise HCC cells to immune checkpoint inhibitors." (PMID 34880251, 2021). "Overexpression of GDF1 induced tumour dedifferentiation toward the ancestral lineage and upregulated a broad panel of CTAs, which also provided a therapeutic window for immune checkpoint inhibitors." (PMID 34880251, 2021). "Our in vivo mouse model demonstrates that GDF1-overexpressing tumours show enhanced cytotoxic T-cell infiltration and higher sensitivity to anti-PD1 therapy." (PMID 34880251, 2021). "Forced expression of GDF1 or addition of GDF1-recombinant protein can induce tumour plasticity in HCC cells, which will then exhibit biomarkers of liver progenitors." (PMID 34880251, 2021). "Overexpression of GDF1 suppresses cell proliferation but strongly enhances tumour dissemination and metastasis." (PMID 34880251, 2021). "Pathological characterisation of the metastatic tumours was further confirmed by H&E staining, and the positive staining of GDF1 was confirmed by IHC." (PMID 34880251, 2021). "Overexpression of GDF1 suppresses cell proliferation but significantly enhances tumour invasion and metastasis both in vitro and in vivo." (PMID 34880251, 2021). "IHC staining of GAGE12E in subcutaneous or intrahepatic xenograft tumours formed by PLC-8024-GDF1 cells or PLC-8024-CTR cells further confirmed the strong upregulation of representative CTAs upon GDF1 overexpression." (PMID 34880251, 2021). "Significant upregulation of GDF1 was found in HCC tumour tissues compared with their paired normal counterparts." (PMID 34880251, 2021). "This exploration confirmed that the GFDs family played a crucial role in GC oncogenesis Our results indicated that GDF1, 3, 6, 7, 10, 15 could be considered as potential tumor biomarker for the diagnosis of GC patients." (PMID 40153751, 2025). "Moreover, it has been proven that the activator of HSP90 ATPase activity 1 (AHSA1) and growth differentiation factor 1 (GDF1) genes are closely related to the tumor progression of HCC." (PMID 38021165, 2023). "Considering the dual role of the TGF-β family in both suppressing cell growth and promoting tumour metastasis, we further examined whether GDF1 affects HCC tumour metastasis." (PMID 34880251, 2021). "Inhibition of the epigenetic modulator LSD1 in GDF1-positive HCC tumours strongly boosted the expression of CTAs, which might further sensitise HCC patients to immune-based therapies." (PMID 34880251, 2021). "Further investigation of the effects of GDF1 on immune cells in the tumour microenvironment might better reveal the roles of GDF1 in antitumour immunity." (PMID 34880251, 2021).
tumor (continued). "We also find that a series of cancer testis antigens (CTAs) are significantly activated in GDF1-overexpressing tumour cells, and this process might be mediated through inhibition of the epigenetic modulator LSD1." (PMID 34880251, 2021). "While GDF1 might potentially serve as an indicator for ICI therapy, considering its strong association with tumour immunogenicity." (PMID 34880251, 2021). "However, overexpression of GDF1 strongly induced tumour dissemination and metastasis both in vitro and in vivo." (PMID 34880251, 2021). "GDF1-induced tumour lineage plasticity might be an Achilles heel for HCC immunotherapy." (PMID 34880251, 2021). "However, there have been limited studies on the role of GDF1 in tumour plasticity." (PMID 34880251, 2021). "In addition, although prometastatic GDF1 is strongly associated with a poor prognosis in C57BL/6 mice, anti-PD1 therapy dramatically reversed malignant progression and significantly prolonged the overall survival of C57BL/6 mice bearing GDF1-overexpressing tumours." (PMID 34880251, 2021). "Similarly, GDF1, which belongs to the transforming growth factor-β, has been confirmed to be highly expressed in high-grade poorly differentiated HCCs, and closely related to poor tumor differentiation, inducing tumor lineage plasticity, and induced tumour metastasis." (PMID 38021165, 2023). "In the present study, GDF1, which belongs to the transforming growth factor-β (TGF-β) superfamily, is found to be highly expressed in poorly differentiated high-grade HCC tumours." (PMID 34880251, 2021). "IHC staining of xenograft tumours further confirmed tumour plasticity and lineage reversion in HCC cells with GDF1 overexpression." (PMID 34880251, 2021). "The expression of GDF1 and the cytotoxic T-cell surface marker CD8, which reflects tumour-infiltrated cytotoxic T cells, was found to be significantly higher in the activated immune group than in the exhausted immune group and the remaining nonimmune group (left)." (PMID 34880251, 2021). "Last but not least, GDF1, 3, 6, 7, and 15 could be considered as potential tumor biomarker for GC patients’ prognosis evaluation." (PMID 40153751, 2025). "Although GDF1-induced cell plasticity enables the malignant transformation of HCC, reactivation of CTAs might be an Achilles heel for immunotherapy in this subtype of tumour." (PMID 34880251, 2021). "The actual mechanism is still not clear, however, it is possible that the presence of GDF1 might prime the tumour microenvironment to favour LSD1 in regulating tumour immunogenicity." (PMID 34880251, 2021).
heart disease (1 paper, 2023). "Congenital heart disease is associated with genetic changes in the GDF1 coding area, and GDF1 is essential for left-right patterning." (PMID 38124890, 2023).
GDF1 also shares sentences with these, for which no sentence is quoted: atrioventricular septal defects (1 paper); breast carcinoma (1); Dermatofibrosarcoma (1); leukemia (1); pulmonary stenosis (1); stomach tumours (1).